ECHDC1 (ethylmalonyl-CoA decarboxylase 1)
Description:
Decarboxylates ethylmalonyl-CoA, a potentially toxic metabolite, to form butyryl-CoA, suggesting it might be involved in metabolite proofreading. Acts preferentially on (S)- ethylmalonyl-CoA but also has some activity on the (R)-isomer (By similarity). Also has methylmalonyl-CoA decarboxylase activity at lower level (By similarity).
Synonyms: MMCD; dJ351K20.2; HEL-S-76
Tractability: PROTAC: ubiquitination databases record sites on it; its protein half-life has been measured.
Gene: Protein-coding gene on chromosome 6 (127,288,712 to 127,343,609, reverse strand). Ensembl gene ENSG00000093144.
Subcellular location: Cytoplasm, cytosol
Subcellular location (Human Protein Atlas): Vesicles
Gene Ontology:
Molecular function: methyl/ethyl malonyl-CoA decarboxylase activity; protein binding; carboxy-lyase activity; catalytic activity
Biological process: fatty acid beta-oxidation
Cellular component: cytosol
Genetic constraint (gnomAD): Loss-of-function variants: 29 observed, 27.23 expected, observed/expected ratio (o/e) 1.07, 90% interval 0.79 to 1.45. The upper end of that interval is the gene's LOEUF score, 1.45, which puts it in group 6 of 6, group 1 being the genes least tolerant of losing a copy. Missense variants: 307 observed, 341.64 expected, observed/expected ratio (o/e) 0.9, 90% interval 0.82 to 0.99. Synonymous variants: 117 observed, 124.74 expected, observed/expected ratio (o/e) 0.94, 90% interval 0.81 to 1.09.
Homologues: Orthologues: chimpanzee ECHDC1 (99% identical), macaque ECHDC1 (98% identical), rabbit ECHDC1 (89% identical), pig ECHDC1 (84% identical), mouse Echdc1 (82% identical), dog ECHDC1 (81% identical), rat Echdc1 (78% identical), tropical clawed frog echdc1 (55% identical), Caenorhabditis elegans C32E8.9 (25% identical). Paralogues in human: AUH (24% identical), ECHDC2 (24% identical), CDYL (23% identical), ECHS1 (21% identical), HIBCH (20% identical), CDYL2 (19% identical), ECI1 (19% identical), ECH1 (19% identical), CDY1B (18% identical), CDY2A (18% identical), CDY2B (18% identical), ECHDC3 (18% identical), and 1 more.
Diseases named in the same sentence as ECHDC1 in open-access papers:
ECHDC1 is named in the same sentence as 9 diseases in open-access papers, as found by Europe PMC text mining. Sharing a sentence is not in itself a finding about the gene and the disease. The quoted sentences say what the papers report.
breast carcinoma (5 papers, 2011 to 2021). "ECHDC1, an enzyme involved in mitochondrial fatty acid metabolism and located in a region implicated in breast cancer by GWAS, showed differential splicing between ER+ and TN subtypes (ANOVA F-test, FDR = 7.95e-08)." (PMID 28263985, 2017). "Interestingly, a previous report based on genome‐wide association study implicated the genomic locus mapping to the ECHDC1 as a breast cancer risk locus in Jewish Asheknazi women." (PMID 33750001, 2021). "In this context, it is noteworthy that a recent large genome-wide association study found a strong association of breast cancer with a polymorphism in the gene encoding enoyl CoA hydratase domain containing 1 (ECHDC1), which also partakes in the integrity of the TFP." (PMID 22240105, 2012). "In particular, ECHDC1 was identified as the most frequent rCCS gene among 24 out of the 106 breast cancer cell lines considered in our analysis." (PMID 33750001, 2021). "Specifically, we showed that the level of succinate increases in breast cancer cells with hypermethylated and lowly expressed ECHDC1." (PMID 33750001, 2021). "Our further analysis of the CLIP signature of ECHDC1 revealed that it was hypermethylated in all the breast cancer cell lines in which it was identified as a rCCS gene." (PMID 33750001, 2021). "Subsequent metabolite profiling of three such intermediate metabolites revealed that succinate and 2OH‐3MBA were significantly up‐regulated in the breast cancer cell lines in which ECHDC1 was identified as a rCCS gene." (PMID 33750001, 2021). "We demonstrated the power of the integrative analyses by identifying a novel driver gene, ECHDC1, with tumor suppressive role validated both in breast cancer cells and patient tumors." (PMID 33750001, 2021). "We reasoned that the down‐regulation of ECHDC1 in breast cancer cells could lead to alteration in the levels of intermediate metabolites resulting in tumorigenesis." (PMID 33750001, 2021). "Of note, recent studies have indicated that ECHDC1 might play a role in the development of breast cancer." (PMID 34419447, 2021). "As an application case, the CLIP framework identified a novel driver gene, ECHDC1, with a hitherto unknown tumor suppressive role in breast cancer." (PMID 33750001, 2021). "However, BT‐474 phenotype remained unaltered after the knockout, further supporting the tumor suppressive role of ECHDC1 in breast cancer cells." (PMID 33750001, 2021). "Notably, neither metabolic profiling nor germline genotyping data were used as part of the CLIP framework, thereby these studies provide an orthogonal support for a previously unappreciated role of ECHDC1 in breast cancer." (PMID 33750001, 2021). "Notably, MOFA+ was unable to identify ECHDC1 as a latent factor shared across data modalities and driving heterogeneity in breast cancer cell lines." (PMID 33750001, 2021). "Interestingly, the 6q22.33 region has been identified as a breast cancer susceptibility locus where two candidate genes are located, that is, RING finger protein 146 (RNF146) and enoyl coenzyme A hydratase domain-containing 1 (ECHDC1)." (PMID 21958427, 2011).
bladder cancer (3 papers, 2018 to 2025). "ECHDC1, as a metabolism-correcting enzyme, is involved in fatty acid synthesis, which is associated with drug resistance in tumors such as bladder cancer, but the specific mechanism of ECHDC in GC still needs to be further studied." (PMID 40191191, 2025). "ECHDC1 encodes for a proofreading enzyme involved in lipid metabolism, with an increased expression observed in resistant bladder cancer cells." (PMID 30208867, 2018). "Silencing ECHDC1 in bladder cancer cell lines induces upregulation of p27, ultimately leading to cell cycle arrest and reduced proliferation." (PMID 39590360, 2024).
breast tumor (2 papers, 2021 to 2024). "A multi-modal meta-analysis has suggested that ECHDC1 can be used as a new breast tumor suppressor." (PMID 39590360, 2024). "We confirmed here the tumor suppressive role of ECHDC1 and highlighted a possible mechanism by which ECHDC1 may contribute to breast tumor growth." (PMID 33750001, 2021). "As an example, CLIP identifies ECHDC1 as a novel breast tumor suppressor." (PMID 33750001, 2021).
Obesity (1 paper, 2018). Accumulation of substantial excess body fat. "Except for these and alcohol dehydrogenase 1B (ADH1B), malic enzyme 1 (ME1) and ethylmalonyl-CoA decarboxylase (ECHDC1), other expressed genes in the cluster have little known information in the context of obesity and chronic diseases." (PMID 30380678, 2018).
cancer (2 papers, 2021 to 2025). A tumor composed of atypical neoplastic, often pleomorphic cells that invade other tissues. "During the identification of effective cancer predictive genes, We initially excluded ATPAF1 (associated with mitochondrial function) and ECHDC1 (involved in fatty acid oxidation) from our analysis because the expression levels of these functional genes are influenced by multiple factors." (PMID 40608007, 2025).
tumor (1 paper, 2021). "To further illuminate the mechanistic basis of the tumor suppressive role of ECHDC1, we investigated the metabolic pathway in which ECHDC1 is involved, namely, the propanoate metabolism." (PMID 33750001, 2021). "In the same cell lines, ECHDC1 mRNA was downregulated, suggesting that ECHDC1 could be a putative tumor suppressor." (PMID 33750001, 2021).
ECHDC1 also shares sentences with these, for which no sentence is quoted: diabetes mellitus (1 paper); ovarian carcinoma (1); schizophrenia (1).